MPO (myeloperoxidase)
Diseases named in the same sentence as MPO in open-access papers (continued):
Sharing a sentence is not in itself a finding about the gene and the disease.
pulmonary hypertension (10 papers, 2013 to 2024). Increased pressure within the pulmonary circulation due to lung or heart disorder. "e., increased W/D ratio), pulmonary hypertension, as well as increased levels of ET-1, NE, MPO, and MDA." (PMID 24098703, 2013). "Citrulline, a biomarker of intestinal mass and absorptive function, has demonstrated efficacy in ameliorating chronic hypoxia-induced pulmonary hypertension and celiac artery obstruction-induced increases in lipid peroxidation, MPO, and inducible nitric oxide synthase (NOS) activity in the stomach." (PMID 38306371, 2024). "The avoidance of pulmonary hypertension is due to the increased expression of GNG2 and CA2 and the decreased expression of TAGLN and MPO, and the increased vascular permeability is due to the increased expression of GNG2 and the decreased expression of GSN." (PMID 36009723, 2022). "MPO also could contribute to the pulmonary hypertension and acute chest syndrome in SCD, since elevated MPO immunoreactivity has been measured in the alveolar epithelium of lung tissues from patients with SCD." (PMID 33669171, 2021).
type 1 diabetes (10 papers, 2015 to 2025). "In a recent study of patients with type 1 diabetes, hsCRP and myeloperoxidase were useful biomarkers for assessing the risk of carotid atherosclerosis." (PMID 37892617, 2023). "It is known that the activity of MPO is inhibited in leukocytes under type 1 diabetes, resulting in diminished phagocytic activity of neutrophils and thus increasing susceptibility to infections." (PMID 33333730, 2020). "In the present study, we evaluated the protective effects of oleuropein onmyeloperoxidase (MPO) activity, nitrite, urea, creatinine and glomerulosclerosis inalloxan-induced type 1 diabetic rats." (PMID 28975102, 2017). "Our data show a rise in MPO levels and a correlation with hs-CRP levels, prompting the hypothesis that this enzyme is also important in the development of microvascular alterations in type 1 diabetes." (PMID 32650465, 2020).
acute lymphoblastic leukemia (9 papers, 2015 to 2025). Leukemia with an acute onset, characterized by the presence of lymphoblasts in the bone marrow and the peripheral blood. "CST3 and MPO were experimentally demonstrated to exhibit a correlation with acute lymphoblastic leukemia (ALL) or AML." (PMID 40338916, 2025). "Recently, isolated myeloperoxidase expression (isoMPO) has been documented in B-acute lymphoblastic leukemia (B-ALL) and several contradictory studies addressed its clinical significance in pediatric patients." (PMID 34319037, 2021). "A 4-year-old boy was diagnosed as having precursor B-cell acute lymphoblastic leukemia (ALL) but with a mixed lympho-myeloid phenotype: positive for myeloperoxidase, CD13+, CD10+ and CD19+." (PMID 26017033, 2015). "In acute lymphoblastic leukemia, the CD26 level is correlated with the myeloperoxidase activity, glutathione-s-transferase activity and xanthine oxidase activity." (PMID 27580693, 2016). "Blasts were negative for myeloperoxidase (MPO), and immunophenotype by flow cytometry was consistent with pre-B cell acute lymphoblastic leukemia (ALL) (positive for CD10, CD19, CD34, HLA-DR, and TdT, negative for CD3, CD5, CD7, and myeloid antigens)." (PMID 32538178, 2020). "Negative results for MPO/SBB and NSE suggest either M0 or M7 or possibly acute lymphoblastic leukemia (ALL)." (PMID 36982453, 2023). "However, the WHO classification does not define the threshold for myeloperoxidase (MPO) positivity, which complicates the diagnosis of ALAL when it presents markers typical of acute lymphoblastic leukemia (ALL) but has MPO as the sole myeloid marker." (PMID 40755566, 2025).
autoimmune vasculitis (9 papers, 2017 to 2025). An autoimmune form of vasculitis. "While MPO-ANCA is primarily linked to autoimmune vasculitis, which can occasionally be accompanied by IP, the presence of MPO-ANCA in this case of SAPHO syndrome raises questions about its chance occurrence or potential association." (PMID 40497194, 2025). "Since several patients who were severely or critically ill had thromboembolic and vascular events, we also analyzed the same 73 patients for Myeloperoxidase (MPO) and Proteinase 3 (PR3) antibodies, as these antibodies are associated with autoimmune vasculitis." (PMID 34521836, 2021). "Here, we studied its role in the pathogenesis of experimental autoimmune vasculitis, a pre-clinical model of myeloperoxidase-ANCA-induced pauci-immune systemic vasculitis in the Wistar Kyoto rat." (PMID 32305129, 2020). "WKY rats immunized with MPO develop experimental autoimmune vasculitis (EAV), which could suggest a role of Cp in the pathophysiology of EAV." (PMID 28450461, 2017). "Seventy-five patients with clinically suspected autoimmune vasculitis (AIV) and 25 healthy volunteers were also tested for anti-myeloperoxidase and anti-proteinase 3 antibodies using IIF, the AtheNA Multi-Lyte® AIV system, and enzyme-linked immunosorbent assay (ELISA)." (PMID 37293321, 2023).
co-infection (9 papers, 2017 to 2025). "MPO+ cells in the lung during SIV/SARS-CoV-2 co-infection were evident in all animals." (PMID 40195984, 2025). "In placental blood, indicators of neutrophil activation, myeloperoxidase (MPO) and proteinase 3 (PRTN3), are significantly elevated with PM and, more profoundly, with PM/HIV co-infection, in association with placental parasite density and hemozoin-bearing leukocyte accumulation." (PMID 34737733, 2021). "Consistent with the present findings that showed that co-infection with Giardia attenuated C. rodentium-induced colonic elevation of MPO, a well-known marker of granulocyte infiltration, recent findings have reported that Giardia was able to cleave CXCL-8, a potent chemoattractant for neutrophils." (PMID 28622393, 2017). "In contrast, placental blood levels of MPO are significantly elevated with PM and PM/HIV co-infection relative to uninfected and HIV+ women, respectively, and in mothers who reported recent fever." (PMID 34737733, 2021). "In placental blood collected from Kenyan women, MPO and proteinase 3 were substantially increased in instances of placental malaria and, more dramatically, in cases of placental malaria/HIV co-infection, correlating with placental parasite density and the accumulation of hemozoin-laden leukocytes." (PMID 40950582, 2025). "We first measured circulating levels of myeloperoxidase (MPO), a neutrophil granule and marker of inflammation, and found that several animals had elevated levels prior to SARS-CoV-2 infection and throughout co-infection, with transient increases observed in a few animals." (PMID 40195984, 2025). "For sCD25 and MPO, the same patterns were seen when those with (n = 49) and without (n = 44) co-infection with HIV were analysed separately." (PMID 30563486, 2018). "Interestingly, despite defects in fungal killing, the neutrophils from co-infected lungs expressed higher levels of reactive oxygen species (ROS) and myeloperoxidase (MPO), suggesting that fungal killing by neutrophils during co-infection occurs independently of ROS and MPO." (PMID 40788118, 2025). "Also inversely, low MPO induction (as seen with the PA14 co-infections) does not better promote S. aureus colonization." (PMID 31921058, 2019). "Hence, the level of inflammation, as inferred by MPO production elicited by P. aeruginosa or the co-infection, does not seem to be involved in the mechanism by which P. aeruginosa helps S. aureus colonization." (PMID 31921058, 2019). "Interestingly, only the co-infection of P. aeruginosa PAC54A and S. aureus CF54A-L resulted in a significantly higher MPO score (vs. the PBS control) even though the level of colonization for both species in that co-infection was much less than that achieved by the PA14–CF54A-L pair." (PMID 31921058, 2019).
enteritis (9 papers, 2010 to 2025). Inflammation of the small intestine. "Oral administration of 5 mg/mL of the extract attenuates indomethacin-induced enteritis in rodents, reducing myeloperoxidase activity, morphometric damage, and liver metallothionein expression." (PMID 37623851, 2023). "DSS-induced enteritis can activate neutrophils in the intestinal tract to produce a large amount of MPO, and this is used as an indicator of the effectiveness of model construction." (PMID 36712538, 2022). "We showed that in MTX group, the level of MPO in rat enteritis intestinal mucosa was significantly higher than it in control group p = 0.000), but in MTX+curcumin group and MTX+NAC group, it was markedly decreased (p = 0.000)." (PMID 20885979, 2010). "MPO can facilitate the production of potent reactive oxygen species (ROS), which in turn sustain inflammation and lead to tissue damage in individuals with enteritis." (PMID 40806121, 2025). "However, the intestinal inflammatory pathological damage was relatively mild in hypoxic mice compared with that in WT C. rodentium‐induced enteritis in MPO‐/‐ mice." (PMID 38415976, 2024). "Subsequently, we further analyzed the results and found that the pathological changes of C. rodentium‐induced enteritis in MPO‐/‐ mice in a normoxic environment were more severe, mainly manifested as obvious submucosal edema and a large amount of neutrophil and macrophage infiltration." (PMID 38415976, 2024). "Meanwhile, a decrease in the MPO content was detected, indicating that the H&E staining results were consistent with the results of the MPO enzyme assay and that the MPO level may serve as an important indicator of enteritis." (PMID 36712538, 2022). "Our research indicated that adding 1%−3% ECP to LP diets decreased MPO activity, suggesting that ECP exerts anti-inflammatory effects and alleviates enteritis." (PMID 40859391, 2025). "The MPO content in the NEG group increased to a level that was significantly different from that in the BLANK group, indicating the effectiveness of the construction of the enteritis model." (PMID 36712538, 2022).
generalized pustular psoriasis (9 papers, 2020 to 2025). A rare and extreme form of psoriasis characterized by the appearance of sterile pustules which can take many patterns. "The role of the gene encoding MPO is especially discussed in the development of generalized pustular psoriasis." (PMID 39409000, 2024). "Research shows that MPO gene mutations affect neutrophil activity, inflammation control, and skin inflammation resolution, highlighting the genetic basis of generalized pustular psoriasis (GPP) and related disorders." (PMID 39456475, 2024). "The role of the gene encoding MPO is especially discussed in the development of generalized pustular psoriasis (GPP)." (PMID 35163760, 2022). "It has been shown that neutrophil phagocytic activity is reduced in MPO-deficient patients with generalized pustular psoriasis, leading to a small degree of infection compared with the MPO-normal patients." (PMID 32817748, 2020). "Interestingly, a recent publication shows that MPO deficiency can also be associated with severe forms of neutrophil dermatosis, i.e., generalized pustular psoriasis and palmoplantar psoriasis." (PMID 37954595, 2023). "Furthermore, missense mutations located close to PTM sites T553 and N323 on MPO could influence the progression of generalized pustular psoriasis and frontotemporal dementia (FTD), respectively." (PMID 36011324, 2022). "Heterozygous and homozygous MPO variants were reported in several cases of generalized pustular psoriasis (GPP) and some of the cases had also one or two IL36RN gene variants and the other had only one or two MPO variants." (PMID 39992598, 2025). "The most common mutation in generalized pustular psoriasis occurs in the IL-36 receptor antagonist gene, though rarer mutations include pathogenic CARD14, AP1S3, and MPO genes." (PMID 39802942, 2025). "Other genes with mutations identified in patients with generalized pustular psoriasis include the adaptor-related protein complex 1 subunit sigma 3 (AP1S3), mutations in Myeloperoxidase (MPO) genes, Serpin Family A Member 1 (SERPINA1) and SERPINA3, TNIP1, and IL1RN." (PMID 38256115, 2024). "The inhibition of T553 and N323 on MPO could influence the progression of generalized pustular psoriasis and frontotemporal dementia (FTD), respectively." (PMID 36011324, 2022).
glomerular disease (9 papers, 2014 to 2025). "In this model, depletion of Tregs by anti-CD25 mAb enhanced the frequencies of MPO-specific IFNγ- and IL-17A-expressing T cells and aggravated glomerular disease, thereby demonstrating the importance of Tregs in the maintenance of tolerance against the MPO autoantigen." (PMID 33496881, 2021). "Some of these glomerulopathies have not been reported in the literature to be associated with CPI use (MPO-ANCA positive pauci-immune glomerulonephritis, C3 staining, or AA amyloid)." (PMID 30612580, 2019). "Still, the lack of response to antibiotics, combined with nephrotic-range proteinuria and positive MPO-ANCA, raised suspicion for glomerular disease." (PMID 40636326, 2025). "Although there was no significant increase in haematuria after re-challenge with MPO plus LPS, when the kidneys were analysed 154 days later, the glomerular injury resembled that at day 56, whereas non-relapsed animals at the same time point had very mild glomerular disease." (PMID 27905491, 2016).
polyarteritis nodosa (9 papers, 2009 to 2025). Polyarteritis nodosa (PAN) is a rare, clinically heterogeneous, rheumatologic disease characterized by necrotizing inflammatory lesions affecting small- and medium-sized blood vessels. "Using this technique, the lymphohistiocytic, periadrenal periarteritis of the Bernese mountain dog showed mild presence of DNA–histone-1 complex positive web-like structures and moderate, extracellular MPO signal surrounding infiltrating macrophages." (PMID 35591872, 2022). "On the other hand, PR3-ANCA-negative sera from patients with polyarteritis nodosa which possibly related to MPO-ANCA and aortitis syndrome as well as control sera from a healthy volunteer did not have any priming effects on PBMCs." (PMID 19594951, 2009). "Furthermore, antibodies against MPO are present in the sera of patients with polyarteritis nodosa 24-26,56-59." (PMID 33746569, 2021). "In one patient, the initial presentation was consistent with polyarteritis nodosa(based on a positive angiogram, rash, and iritis) but she subsequently developed an MPA disease pattern, with pauci- immune glomerulonephritis and MPO-ANCA." (PMID 21682926, 2011). "Titers of PR3-ANCA and MPO-ANCA in serum from WG patients, polyarteritis nodosa patients, and aortitis syndrome patients used in this study." (PMID 19594951, 2009). "The value of LAMP-2-ANCA seropositivity as a biomarker may be greatest among AAV patients who have MPO/PR3-ANCA-negative SVV, but more so in individuals with middle vessel vasculitis (MVV), namely, polyarteritis nodosa (PAN) and large vessel vasculitis (LVV), namely Takayasu’s arteritis (TAK)." (PMID 38612581, 2024). "One of our cohort was initially diagnosed with polyarteritis nodosa (positive angiogram, negative ANCA) but subsequently their disease evolved into MPA, with evidence of pauci-immune glomerulonephritis and MPO-ANCA positivity." (PMID 21682926, 2011). "Antineutrophil cytoplasmic antibodies (ANCA), including proteinase 3- (PR3-) ANCA and myeloperoxidase- (MPO-) ANCA, were negative and hepatitis B virus (HBV) antigen (HBs antigen) and antibody (HBs antibody) which suggest the possibility of polyarteritis nodosa were also not detected." (PMID 27034879, 2016).
rapidly progressive glomerulonephritis (9 papers, 2012 to 2025). Inflammation of the glomeruli that is characterized by a rapid loss in renal function with glomerular crescent formation observed on biopsy; it is often seen in patients with concomitant autoimmune disease, like Goodpasture's syndrome or systemic lupus erythematosus. "Here we describe the first two cases of MPO-ANCA-associated CrGN in ADPKD patients who presented with rapidly progressive glomerulonephritis (RPGN), severe proteinuria, and microscopic hematuria." (PMID 23617397, 2013). "Patients with SLE-AAV overlap syndrome are mostly female, commonly present with rapidly progressive glomerulonephritis (RPGN), and have both antinuclear antibodies (ANA) and anti-myeloperoxidase (anti-MPO) antibodies." (PMID 41357727, 2025).
respiratory infections (9 papers, 2016 to 2026). "Similar associations were reported for MPO levels in respiratory specimens and the risk of respiratory infection." (PMID 38576857, 2024). "We found that plasma MPO concentration was genetically associated with increased risks of respiratory infections (URTI: OR = 1.135, 95% CI = 1.011–1.274, P=0.032; LRTI in the critical care units: OR = 1.323, 95% CI = 1.006–1.739, P=0.045)." (PMID 38576857, 2024). "In another study of patients with IIM, it was found that the serum levels of IL-6, NE and MPO-DNA complexes were higher in subjects with respiratory infections and ILD (Reviewed in 47)." (PMID 36923415, 2023). "Our study found that circulating NE, MPO, and IL-6 were significantly elevated in both ASS and DM patients with comorbid respiratory infections and have good diagnostic value." (PMID 36199667, 2022). "Elevated serum NE, MPO, and IL-6 levels are suggestive of respiratory infections, whereas decreased circulating IL-6 is predictive of RP-ILD." (PMID 36199667, 2022). "Above results indicated a strong performance of MPO, NE, and IL-6 to identify patients with possible respiratory infections." (PMID 36199667, 2022). "In the cardiovascular system, it can determine cardiac hypertrophy; in the immunologic system, it reduces the recovery rate after illnesses and increases the rate of respiratory infections, and decreases myeloperoxidase expression in leukocytes and the small intestine." (PMID 36611353, 2022). "The main causes of death were respiratory infection and DAH in MPO-ANCA positive MPA-ILD." (PMID 33452394, 2021). "Also, anti-MPO AAV is reported to be associated with respiratory infections, but not anti-PR3 AAV." (PMID 37895021, 2023). "All in all, we have demonstrated that elevated IL-6 in serum is not a predictor of RP-ILD, elevated circulating NE, MPO, and IL-6 all suggest respiratory infections, and finally, AAT is an indicator of poor lung function in ASS and DM patients." (PMID 36199667, 2022). "Although respiratory infections are an important predisposing factor for RP-ILD, the results of this study tell us very clearly that elevated IL-6 suggested infection rather than RP-ILD, and that the combined NE and MPO assays provide better clarity." (PMID 36199667, 2022). "MPO (P = 0.049), NE (P = 0.049), and IL-6 (P = 0.014) were significantly higher in ASS and DM patients with respiratory infections compared to patients without respiratory infections." (PMID 36199667, 2022).